TNF (tumor necrosis factor)
Diseases named in the same sentence as TNF in open-access papers (continued):
Sharing a sentence is not in itself a finding about the gene and the disease.
psoriasis (continued). "Another anti-TNF-α monoclonal antibody used to treat psoriasis is efalizumab." (PMID 35204165, 2022). "Moreover, in people suffering from depression, previous studies have shown an increase in proinflammatory cytokines such as TNFα and IL-6, similar to that in psoriasis." (PMID 35163689, 2022). "In the pathogenesis of psoriasis, IL-17 interacts with keratinocytes to promote the production of antimicrobial peptides, proinflammatory cytokines and chemokines (IL-1β, TNF-α, IL-6, IL-17C, CXCL1, CXCL3, CXCL5, CXCL8 [IL-8] and CCL20) and proliferative cytokines (IL-19)." (PMID 35514987, 2022). "In addition, the difference between CD and UC in psoriasis development after anti-TNF treatment was also assessed." (PMID 35801760, 2022). "Moreover, KYNU is also synergistically regulated by proinflammatory cytokines IL17 and TNFα that play a central role in the pathogenesis of psoriasis." (PMID 35327421, 2022). "The elevated production of inflammatory cytokines observed in psoriasis, such as TNF-α and IFN-γ, might mediate the development of anxiety and depression." (PMID 35209199, 2022). "In our study, serum levels of lL-6 and TNF-α from psoriasis-like mice were elevated." (PMID 35589679, 2022). "In conclusion, our findings suggest that while AD and psoriasis represent distinct pathologies, they may share a potential for future therapeutic benefit through microbial manipulation of the TNF axis and/or through environmental mitigations." (PMID 36605199, 2022). "TNF-a plays a fundamental role in the macrophage response and in the tubercular granuloma formation and the use of TNF-a inhibitors (TNFi) in patients with psoriasis has been associated with tuberculosis reactivation or disease worsening." (PMID 35203438, 2022). "The expert opinion algorithm the authors propose includes IL-17 inhibitors as a first option and IL-23 inhibitors as a second therapeutic option for patients with psoriasis and concomitant hepatitis B virus infection, while TNF-alpha inhibitors should be avoided." (PMID 35741329, 2022). "In this mechanism, stimulated keratinocytes function as the trigger of psoriasis by secreting cytokines, chemokines, and antimicrobial peptides (AMPs) to activate DCs which secret multiple proinflammatory cytokines such as TNF-α, interleukin (IL)-6, IL-12, IL-23 and IL-36." (PMID 36620087, 2022). "Concomitantly, mTOR signaling pathway in turn enhances keratinocytes to produce proinflammatory molecules, including IL-6, CXCL8 and VEGF in response to TNF-α, suggesting that a feedback loop driven by mTOR signaling triggers and aggravates the pathogenesis of psoriasis." (PMID 35938153, 2022). "Moreover, a variety of pathways by AP-1 mediate the inflammatory response of psoriasis, such as TNF-α and IL-17." (PMID 35277199, 2022). "While KYNU relevance to inflammation has been demonstrated in psoriasis in which epithelial cells only expressed KYNU after stimulation with IFNγ or TNFα; and combining the cytokines significantly enhanced IDO and KYNU in various cell types as much as 100 fold." (PMID 36499104, 2022). "Consequently, SHP2‐mediated TLR7/NF‐κB activation was augmented, leading to further increases in the expressions of psoriasis‐related inflammatory cytokines, including IL‐23A, TNF‐α, IL‐6, and IL‐1β, thus accelerating psoriasis‐like skin inflammation." (PMID 34936223, 2022). "It has also been reported that alopecia may be related to psoriasis itself or systemic therapies used to treat it especially anti-TNF-α agents." (PMID 36059983, 2022). "Moreover, the anti-inflammatory activity of active constituents on a TNF-α/IL-17A/IFN-γ-stimulated human keratinocyte psoriasis model was also evaluated." (PMID 36015080, 2022). "Moreover, better outcomes of trials addressing TNF-α inhibitors as a treatment in psoriasis patients reflect the critical role of this cytokine in the immunopathogenesis of psoriasis." (PMID 35889927, 2022). "Together with IL-17, TNF-α contributes to the pathogenesis of psoriasis." (PMID 35686132, 2022).
psoriasis (continued). "Therefore, a potentially interesting connection exists between KRT31 and psoriasis as well as the efficacy of TNF blockade." (PMID 36059983, 2022). "Additionally, it is well known that patients with psoriasis obtain benefits from anti-TNF-α therapy, especially for patients with metabolic syndrome concomitantly." (PMID 35455298, 2022). "Tumor necrosis factor-α inhibitors (adalimumab, certolizumab, etanercept, or infliximab) showed a protective cardiovascular profile in multiple, mainly observational studies of psoriasis." (PMID 35755028, 2022). "Monoclonal antibodies inhibiting IL-17 signaling and newer IL-12/23 antagonists may offer even greater disease control in pediatric psoriasis with similar or fewer SAEs than TNF-inhibitors." (PMID 36226155, 2022). "TNF alpha inhibitors are the cornerstone in the treatment of psoriasis with biologics." (PMID 35566548, 2022). "It is well known that TNF-α is positively correlated with psoriasis." (PMID 36035406, 2022). "However, it should be noted that TNF-α blockades are relatively less effective in AD compared to psoriasis, which has been established as a therapeutic choice along with IL-17 inhibitors and IL-23 inhibitors." (PMID 36362483, 2022). "TNF-α /IL-17A/ IFN-γ are known to be psoriasis-inducing mediators in the immune system of skin." (PMID 36015080, 2022). "In particular, the most commonly reported was psoriasis, which is a paradoxical skin reaction since it may be both induced and treated with anti-TNF." (PMID 35203664, 2022). "The strength of our study is that it comprehensively demonstrated that anti-TNF treatment did not influence the paradoxical development of psoriasis and the types of anti-TNF agents were not related to the risk of psoriasis in IBD patients." (PMID 35801760, 2022). "Indeed, the implementation of TNFα blockers into the clinic revolutionized the management of psoriasis and other chronic inflammatory diseases." (PMID 35812457, 2022). "The current clinical treatment of psoriasis completely involves topical drugs, including vitamin D3 analogues, topical corticosteroids, calcineurin inhibitors, keratolytics, and biologics that inhibit TNF-α, IL-12, IL-13, IL-17, and IL-23." (PMID 35813890, 2022). "In contrast, patients with secukinumab or ustekinumab as the index drug had the lowest frequency of switching to other PSObio drugs; however, it should be noted that these groups are also the least numerous, as these drugs were approved for psoriasis later than anti-TNF drugs." (PMID 35682382, 2022). "In classical psoriasis, pDC-derived IFNα activates myeloid DCs to produce TNF and IL23." (PMID 35207521, 2022). "Moreover, psoriasis is characterized by increased expression of TNF-α and IL-6 in lesions, and TNF-α is a verified drug target in psoriasis and other autoimmune diseases, such as inflammatory bowel disease (IBD) and RA." (PMID 36110097, 2022). "The result may illustrate that TNF-α blocking agents protect psoriasis patients from AD on molecular levels." (PMID 35669784, 2022). "As the immunologic pathophysiology of psoriasis is being more clearly elucidated, biologics, such as tumor necrosis factor (TNF)-α inhibitors, interleukin (IL)-12/23 inhibitors, and IL-17 inhibitors, have recently emerged as main treatment options for psoriasis." (PMID 36450739, 2022). "The efficacy of TNF-α inhibitors against psoriasis underscores the importance of this cytokine in the disease, although the percentage of patients that experience marked improvements in their conditions is significantly lower than is the case after treatment with IL-17 or IL-23 inhibitors." (PMID 35884790, 2022). "As adiponectin inhibits the production of TNF-α, which has a potential pro-inflammatory role in both psoriasis and AD, low levels of adiponectin may be expected in both chronic inflammatory skin diseases." (PMID 36362483, 2022).
psoriasis (continued). "Given the overall safety and efficacy data investigated in this systematic literature review and meta-analysis, the newer IL12/23- and IL17-targeting biologics seem preferable to the older TNF inhibitors for a majority of pediatric patients with moderate-to-severe psoriasis." (PMID 36226155, 2022). "Namely, TNF-α blockers may potentially suppress the Th2 response, thus becoming an alternative therapy for BP, especially when accompanied by psoriasis." (PMID 36685489, 2022). "More recently, more focus has been given to TNF-α mediated necroptosis, an alternative mode of regulated cell death, which contributed to neurodegenerative disease, cancer, and myocardial ischemia-reperfusion injury, as well as psoriasis." (PMID 36017227, 2022). "In addition, etanercept reduced the levels of TNF‐α and IL‐6/12/23, and enhanced the levels of IL‐4/10, reduced Th17/Treg ratio and facilitated the polarization of macrophages to M2 in psoriasis model mice." (PMID 36444619, 2022). "In the current study, coptisine inhibited the LPS-induced secretion of TNF-α and IL-1β in BV2 microglial cells, suggesting that coptisine might attenuate psoriasis-associated neuroinflammation by suppressing microglial activation." (PMID 35209199, 2022). "However, the importance of both TNF and skin lipid biology have been established in the pathogenesis of psoriasis." (PMID 36605199, 2022). "TNF inhibitors can also induce multiple sclerosis–like syndromes, psoriasis, and vasculitis." (PMID 35104241, 2022). "Hence, the downstream TNF-α signaling pathways that play a role in exacerbating psoriasis can be inhibited/blocked." (PMID 35203707, 2022). "TNFα has a well-established role in the pathogenesis of psoriasis." (PMID 36605199, 2022). "Inflammatory factors such as TNF-α, IL-23, and IL-17 contribute to the pathogenesis of psoriasis." (PMID 35795567, 2022). "In this study, we used HaCaT keratinocytes stimulated with M5, a cocktail of five inflammatory cytokines (TNF-α, oncostatin M, IL-1α, IL-17A, and IL-22), as an in vitro model of psoriasis with typical upregulation in the production of cytokines, chemokines, and antimicrobial peptides." (PMID 36555642, 2022). "Moreover, the horny cell of the patients with psoriasis can secrete IL-6, TNF alpha, IL-1 alpha, glucocorticoids, among others." (PMID 35948962, 2022). "The prevalence of having depression or anxiety is higher in psoriasis patients than in controls, and TNF-α could be a pathophysiologic link between the two conditions." (PMID 34829740, 2021). "A randomized prospective open-label study reported that the risk of onychomycosis in psoriasis patients receiving treatment with an antitumor necrosis factor (anti-TNF) was 20.3% compared to 13.9% in patients that did not receive any biological agents." (PMID 34938812, 2021). "In general, the serum levels of the psoriasis patients had increased levels of TNF-α and IgG2a." (PMID 34641629, 2021). "In the pathophysiology of psoriasis, tumor necrosis factor-α plays a crucial role." (PMID 34834393, 2021). "The exact etiology of psoriasis remains unclear, but nowadays, most treatments involve inhibition of tumor necrosis factor-alpha (TNF-α) production that plays a significant role in skin inflammation." (PMID 34201974, 2021). "Interestingly, TNF-inhibitors have shown efficacy and are successfully used in psoriasis and other inflammatory skin conditions." (PMID 33805042, 2021). "Anti-TNF-α drugs, known as pioneers of the biological therapy of psoriasis, mediate their action by impairing the interaction of DCs and T lymphocytes, i.e., by preventing the synthesis of IL-23; therefore, their clinical effect is mostly associated with suppressing the IL-23/Th17 axis." (PMID 34769005, 2021). "It is known to be induced by TNFα, but not other psoriasis-associated cytokines, and has been shown to bind with high affinity to the tumor necrosis factor receptor family member TMEM149 (renamed Igflr1)." (PMID 34445339, 2021).
psoriasis (continued). "Most of the inflammatory markers involved in Psoriasis (TNF-α, IL-2, IL-6, IL-23, IL-1β, IL-10), and increased serotonin transporters (5-HTT) were also found in the pathogenesis of depression, showing the immune-inflammatory linkage between psoriasis and major depression." (PMID 34183985, 2021). "Encapsulated naringenin seemed to be more active than naringenin alone, therefore, in this context, the inhibition of TNF-α blocked their activity, and this could reduce the interaction among the immune system and keratinocytes in psoriasis." (PMID 34943117, 2021). "Finally, new targets have been introduced in the treatment algorithm for moderate-to-severe psoriasis, which has proved more effective than drugs than inhibit TNF or IL-12, IL-17 and IL-23." (PMID 33921427, 2021). "To assess the function of PI3Kδ in psoriasis skin, we evaluated the effects of a potent, ATP-competitive, and selective PI3Kδ inhibitor—seletalisib—on the key intracellular pathways known to be activated by IL-22 or TNF-α in human keratinocytes." (PMID 34685616, 2021). "This may result from elevated proinflammatory cytokines in psoriasis-TNF, IL-17, IL-1 and IL-6, which are known to inhibit melanogenesis and specifically PKA, MITF, TYR and DCT." (PMID 34884858, 2021). "In addition to the TNF-α inhibitors, three anti-IL-17 biologics, namely, secukinumab, ixekizumab, and brodalumab, are used for psoriasis." (PMID 34371756, 2021). "The adverse effects of TNF inhibitors mainly included infection, increased risk of TB and hepatitis B virus (HBV) infection, injection site reaction, abnormal liver function, severe allergic reaction, autoimmune disease, new onset of psoriasis, and tumors." (PMID 34552481, 2021). "Besides TNF, IL-12 is a key inflammatory cytokine reported to be involved in early psoriasis pathogenesis." (PMID 34215755, 2021). "TNF-α induces the proliferation and anti-apoptosis of keratinocytes via the NF-κB signal pathway, eventually leading to the formation of microabscess by enhancing the recruitment of inflammatory cells in psoriasis." (PMID 33800290, 2021). "In addition, TNF-α, IL-6, and IL-1β are important proinflammatory cytokinesthat are related to the pathogenesis of psoriasis." (PMID 34202301, 2021). "Moreover, psoriasis patients treated with TNF blockers display reduced numbers of ILC3s suggesting their role in psoriasis pathogenesis." (PMID 34938670, 2021). "TNF-α inhibitors are the first-generation biologics for psoriasis." (PMID 34371756, 2021). "In addition, anti-TNF treatment in patients with paradoxical psoriasis prolonged type I IFN production by pDCs through inhibition of their maturation." (PMID 33441439, 2021). "During anti-TNF-a treatment, the BMI of patients with psoriasis increase significantly." (PMID 34372872, 2021). "This was a reason for using TNF-α inhibitors in therapy of moderate and acute psoriasis." (PMID 33562571, 2021). "Moreover, PPPs were observed to remarkably inhibit the levels of psoriasis-related pro-inflammatory mediators in the serum, namely, IL-17, IL-6, TNF-α, IL-8, and IL-23." (PMID 35153762, 2021). "Interestingly, adipose tissue also produces large amounts of proinflammatory cytokines, including TNF-α, IL-6 and IL-17, contributing to worsening of psoriasis." (PMID 34068473, 2021). "Finally, tumor necrosis factor-alpha (TNFα) is a key cytokine that is upregulated in psoriasis; indeed, anti-TNFα medications have been successfully used to treat psoriasis." (PMID 34445455, 2021). "Anti-TNF therapy has also been found to decrease IL-6 levels in patients with psoriasis." (PMID 34372872, 2021). "TNF-α is well-known as a potent proinflammatory cytokine in psoriatic skin lesions, whereas IFN-γ has been recognized as one of the pathogenic cytokines that can trigger inflammatory cascades of psoriasis with the potential to become a severity marker." (PMID 35004790, 2021).
psoriasis (continued). "A retrospective cohort study among RA and psoriasis patients revealed a decreased risk of diabetes mellitus among patients treated with TNF-α inhibitors compared with those treated with other nonbiologic agents." (PMID 34803716, 2021). "Etanercept is a TNF alpha blocker used in the treatment of psoriasis." (PMID 33585138, 2021). "IL-24 is a member of the IL-20 family induced by IL-6, TNF, and IL-1β in psoriasis." (PMID 34054833, 2021). "TNF-alpha is elevated in psoriasis, RA, psoriatic arthritis, JRA, and ankylosing spondylitis." (PMID 34065644, 2021). "However, head-to-head studies (anti-IL17 vs. anti-TNFα) for patients with both psoriasis and PsA showed that ixekizumab was superior to adalimumab in the achievement of simultaneous improvement of joint and skin disease (combined ACR50 and PASI100)." (PMID 34680599, 2021). "TNF-alpha antagonists have therapeutic effect in active psoriasis." (PMID 33936220, 2021). "The median values of TNF alpha, IL-17 and IL-23 in patients with psoriasis before phototherapy was significantly higher compared to the control group (10.45 pg/mL vs. 6.33 pg/mL, p = 0.003; 30.49 pg/mL vs. 14.65 pg/mL, p < 0.0001; 94.12 pg/mL vs. 64.41 pg/mL, p < 0.0001)." (PMID 34208603, 2021). "In addition, we have shown that IL-33 administered in combination with SP strongly increases the gene expression of TNF in human mast cells in vitro—an effect that would also occur in psoriasis mediated by neurotransmitters." (PMID 34360845, 2021). "However, ARDS has been reported in patients with psoriasis under anti-TNF-α therapy (etanercept), in which the patient was affected by multiple comorbidities including obesity, hypertension, diabetes, and chronic renal failure." (PMID 34938746, 2021). "On the basis that during the development of psoriasis, responsible immune cells (T cells) extensively secrete TNF-α, which then play a significant role in the pathogenic process, there has been an attempt to develop TNF-α inhibitors as an optional therapy for psoriasis." (PMID 35056961, 2021). "Mixed cytokines, including IL-17A, IL-22, oncostatin M, IL-1α, and TNF-α (M5), are used to simulate HaCaT keratinocytes in vitro to establish a psoriatic keratinocyte model that generates some common phenotypic features of psoriasis." (PMID 34202301, 2021). "Dermatological treatment of psoriasis allows continuing anti-TNF-α in half of them." (PMID 33802483, 2021). "There is evidence that TNF-α inhibitors may have favorable effects on certain conditions of metabolic syndrome in the management of psoriasis." (PMID 34803716, 2021). "MMP9 is regulated by tumor necrosis factor-alpha (TNF-α), which plays a central role in psoriasis." (PMID 34715781, 2021). "In the last 20 years, therapeutics that directly target these cytokines (e.g., TNF or IL-17 inhibitors) completely revolutionized PsO treatment, allowing the complete clearing of psoriasis in a number of patients; however, the latter drugs account for PsA disease control only in ≤50% of patients." (PMID 34631754, 2021). "Interestingly, TNF-α and IL-17, cytokines known to impair bone formation, are central players in the pathogenesis of psoriasis." (PMID 34660638, 2021). "For instance, in mouse chondrocytes, miR-193b-3p downregulates TNF-α, which is an important inflammatory factor in psoriasis pathogenesis, suggesting that dysregulated miR-193b-3p in psoriatic lesions may also contribute to the psoriatic inflammatory response." (PMID 34667159, 2021). "Especially IL-17A and TNF-α display an important inflammatory effect in the pathogenesis of psoriasis, whereas only IL-22, but not IL-17A and TNF-α, cause epidermal alterations typical for psoriasis such as acanthosis." (PMID 33801280, 2021). "TNF inhibition with anti-TNF therapy leads to an ongoing IFNI-mediated inflammation in psoriasis." (PMID 34298932, 2021). "IL-17A is important in relieving psoriasis by upregulating cytokines IL-6, IL-1β, and TNF-α." (PMID 34054833, 2021).